METTL3 (methyltransferase 3, N6-adenosine-methyltransferase complex catalytic subunit)
Diseases named in the same sentence as METTL3 in open-access papers (continued):
Sharing a sentence is not in itself a finding about the gene and the disease.
tumor (continued). "Elevated NFAT5 expression increases the expression of gluconeogenesis-related genes GLUT1 and PGK1, leading to enhanced aerobic glycolysis, proliferation and tumor metastasis in ICC.METTL3 is a poor prognostic factor for ICC patients." (PMID 39289775, 2024). "We demonstrate that inhibiting METTL3 augments tumour immunogenicity and sustains T‐cell function, thereby enhancing responsiveness to ICB therapy." (PMID 39568154, 2024). "In AML, METTL3 promotes the drug sensitivity of tumor cells to Ara-C by inhibiting autophagy in AML cells." (PMID 39468015, 2024). "Knocking down METTL3 can boost anti-tumor immunity and reduce PD-L1 expression, thus alleviating the progression of BC." (PMID 39054967, 2024). "Some researchers have found that METTL3-mediated m6A methylation can not only affect the differentiation of T cells but also maintain the inhibitory effect of Tregs on the tumor-killing function of CD8+ T cells." (PMID 39033180, 2024). "It provides novel insights into the molecular mechanisms of METTL3-induced tumor progression in RCC under prolonged hypoxia and identifies potential therapeutic targets specific to advanced RCC." (PMID 38233403, 2024). "In summary, our findings unveil a signaling network involving METTL3/FGF2/PI3K/AKT/mTOR in LUAD and shed light on the molecular mechanism underlying tumor malignant progression while holding great significance for targeted therapy in research on LUAD." (PMID 39497721, 2024). "For example, lactate accumulation in the CRC TME has been shown to upregulate methyltransferase-like 3 (METTL3) in tumor-infiltrating myeloid cells (TIMs)." (PMID 39659524, 2024). "This suggested that the knock-down of METTL3 can suppress the mitochondrial fusion and tumor growth of CRC cells." (PMID 38549713, 2024). "By catalyzing m6A on functional critical transcripts, METTL3 regulates gene expression and plays a significant oncogenic role in most types of cancers, except for a tumor-suppressive function in renal cell carcinoma and endometrial tumors." (PMID 38322265, 2024). "LINC02038, subjected to METTL3-mediated m6A modification, was a tumor suppressor and decreased in CRC." (PMID 38688909, 2024). "In CRC, overexpression of METTL3 leads to the methylation of pri-miR-1246 and promotes its maturation, which is positively correlated with tumor metastasis." (PMID 39295872, 2024). "Mechanistically, the enhanced level of METTL3 inhibited tumour immune cell infiltrations and upregulated PD‐L1 expression." (PMID 38332508, 2024). "Immunohistochemistry on tumor specimens from in vivo experiments also suggested that in the low-expression METTL3 group, both subcutaneous tumors and lung metastases showed significantly reduced expression of VIM and SNAIL proteins." (PMID 38605400, 2024). "METTL3 can affect tumor development by regulating the level of m6A modification in mRNA of several key oncogenes or tumor suppressor genes." (PMID 38267663, 2024). "Taken together, these results suggest that targeting METTL3 represents a promising therapeutic strategy for enhancing the efficacy of anti‐tumour immunotherapy." (PMID 39568154, 2024). "The increased METTL3 expression in resistant tumor cells enhances the m6A modification of FAM120A mRNA." (PMID 38565940, 2024). "In conclusion, our study underscores the therapeutic potential of METTL3 inhibition in combination with anti‐PD‐1 therapy for effective tumour elimination." (PMID 39568154, 2024). "METTL3, a pivotal catalytic enzyme, plays a crucial role in m6A methylation, influencing the proliferation, migration and drug resistance of tumour cells." (PMID 39580709, 2024). "Knockout of METTL3 in xenograft mouse tumor model also exhibits the impaired glucose uptake and inhibited tumor growth." (PMID 38721006, 2024). "HE staining and statistical analysis revealed that METTL3 KO significantly inhibited the ability of tumour cells to colonize the lungs of injected mice." (PMID 38238831, 2024).
tumor (continued). "A pan-cancer analysis leveraging data from TCGA revealed that, in contrast to normal tissues, mRNA expression levels of METTL3 are significantly upregulated in tumor tissues, whereas the expression levels of METTL14 remain unchanged." (PMID 38965238, 2024). "Some retrospective studies have demonstrated that METTL3 in GC is the main cause of poor overall survival and is correlated with advanced PT, PN, and TNM stages; a tumor size greater than 5 cm; and vascular infiltration." (PMID 39678510, 2024). "Research has shown that METTL3 is overexpressed in various tumours and is closely related to the biological behaviours of tumour cell proliferation, invasion and metastasis." (PMID 38429907, 2024). "YTHDC1 has been shown to promote enhanced cyclization of circlGF2BP3 by METTL3 and increase PD-L1 expression in tumor cells." (PMID 39033180, 2024). "Although we have performed METTL3 KO using CRISPR‐Cas9 and overexpressed WT/mutant forms of METTL3 in tumour cells." (PMID 39568154, 2024). "Consistent with the in vitro results, tumor growth was slowed and xenograft weight was reduced when implanted with METTL3 knockdown A549 cells relative to control (sh-NC) cells." (PMID 38221933, 2024). "Future research on METTL3 in PCa should mainly focus on tumor angiogenesis, glycolipid metabolism, maintenance of tumor stem cells, and its effect on the tumor microenvironment." (PMID 38166703, 2024). "Taken together, YTHDF2 is likely the downstream executed reader following METTL3 targeting, thus playing a pivotal role in the anti‐tumour response." (PMID 39568154, 2024). "A recent study reveals that EBV EBNA1 promotes the degradation of the METTL3 protein via the K48-linked ubiquitin pathway, decreasing TLR9 m6A modification and YTHDF1-enhanced translation, thus promoting tumor immune evasion." (PMID 39695216, 2024). "In a cohort of patients with OSCC, high METTL3 expression was correlated with low disease-free survival and high tumor grade and lymph nodes metastasis, indicating that METTL3 overexpression is related to OSCC poor prognosis." (PMID 38355684, 2024). "EBNA1 facilitates the degradation of the METTL3 protein via the K48-linked ubiquitin pathway, reducing TLR9 m6A modification and YTHDF1-enhanced translation, thus promoting tumor immune evasion." (PMID 39695216, 2024). "In ovarian carcinoma, the depletion of METTL3 in NK cells inhibits cell infiltration ability and functions, leading to accelerated tumor development through a reduction in SHP-2 expression and AKT and MAPK signaling pathway activation." (PMID 39759516, 2024). "In this study, we functionally validated the relationship between T cells targeting METTL3 and anti‐tumour immunity." (PMID 39568154, 2024). "For example, METTL3 stimulates tumor proliferation of DLBCL through PEDF-mediated Wnt/β-catenin apoptotic signaling repression." (PMID 39497033, 2024). "In Testicular germ cell tumors (TGCTs), METTL3 protein levels decreased, tumor growth was evident, and patient survival decreased." (PMID 39072324, 2024). "In summary, current research on METTL3 in immunotherapy primarily concentrates on the impact of RNA m6A modification on immune‐related mRNA metabolism in tumours, as well as on enhancing tumour immunogenicity to affect T‐cell function." (PMID 39568154, 2024). "The silencing of METTL3/YTHDF1 inhibit OC progression and mechanistic study reveals that METTL3/YTHDF1 axis enhanced the expression of the tumor-promoting DDR2 to foster the progression of OC." (PMID 38544837, 2024). "In papillary thyroid carcinoma (PTC), METTL3 is able to cooperate with YTHDF2 to inhibit IL-8 secretion, reduce tumor-associated neutrophil (TAN) recruitment, and inhibit tumor growth using c-Rel and RelA as downstream modification targets." (PMID 39072324, 2024). "The loss of METTL3 inhibits YTHDF1-mediated SPRED2 translation and further enhances the activation of NF-kB and STAT3 through the ERK pathway, ultimately mediating tumor growth and metastasis." (PMID 39759516, 2024).
tumor (continued). "In the self-renewal glioblastoma stem cell (GSC), the knocking down of METTL3 significantly promoted tumor progression and shortened the lifespan of GSC-grafted animals." (PMID 38966069, 2024). "METTL3 depletion in macrophages reshapes the tumor microenvironment by enhancing M1- and M2-like TAM phenotypes." (PMID 39759516, 2024). "In terms of its impact on cancer biology, METTL3 exerts control over the translation of numerous target mRNAs involved in tumor progression and apoptosis." (PMID 39333489, 2024). "In tumor cells, aberrant expression and activity of METTL3 can lead to changes in m6A modification levels, thereby influencing tumor initiation, progression, and metastasis." (PMID 39295872, 2024). "The impact of Mettl3–lecKO on lymphangiogenesis and its potential synergy with neovascularization was assessed using a tumor model." (PMID 39372388, 2024). "Studies have found that knockdown of METTL3/14 reduces methylation levels, inhibits cell proliferation, and accelerates apoptosis, leading to inhibition of tumor growth." (PMID 38711100, 2024). "In models with METTL3 depletion, the therapeutic efficacy of PD-1 blockade was reduced, leading to accelerated tumor progression and distant metastasis." (PMID 38902779, 2024). "Our observations of elevated METTL3 levels in the advanced-stage PCa cell lines and high-grade PCa tumor samples are in line with previous evidence that showed the upregulation of METTL3 in advanced-stage PCa." (PMID 38610981, 2024). "Quercetin, a natural compound, inhibits METTL3 activity, reduces m6A modifications, and, thus, inhibits tumor cell proliferation and migration, providing new insights into the development of natural product-based anticancer drugs." (PMID 39295872, 2024). "In this article, we focus on the relationship between METTL3 and tumour cell proliferation, migration, glycolysis and cuproptosis." (PMID 38429907, 2024). "On the other hand, decreased METTL3 levels impair tumor growth by reducing m6A methylation and inhibiting malignant transformation in glioblastoma." (PMID 38665783, 2024). "METTL3 also regulates the biological processes of tumor formation and progression, either as an oncogene, or by regulating other oncogenes." (PMID 38961497, 2024). "We have used STM2457, a pharmacological inhibitor of METTL3, to explore the therapeutic effect of METTL3 inhibition in tumour therapy." (PMID 39568154, 2024). "For example, inhibition of METTL3 expression combined with the glycolytic inhibitor 2-deoxyglucose has a role in delaying tumor progression in HCC." (PMID 39033180, 2024). "Using the CCK8 assay, we observed that METTL3-KD increased tumor cell viability, while overexpression of METTL3 decreased tumor cell viability, indicating that METTL3 inhibits tumor cell proliferation." (PMID 39497721, 2024). "METTL3 has an oncogenic function in most cancers but has also been shown to be a tumor suppressor in some cases." (PMID 38166703, 2024). "By inhibiting METTL3 expression in pancreatic cancer, tumor sensitivity to a variety of chemotherapeutic agents and radiation therapy can be improved." (PMID 39033180, 2024). "The m6A modification plays an indispensable role in maintaining the tumor infiltration and cytotoxicity of NK cells, primarily regulated by METTL3, METTL14, and YTHDF2." (PMID 39372415, 2024). "At the end of the experiment, the tumor volumes and weights in the sh-METTL3 group were significantly lower than those measured in the sh-control group, and these effects were reversed by overexpression of RRM2B or OPA1." (PMID 38549713, 2024). "The lactylation-driven Mettl3-mediated modification of RNA m6A promotes immunosuppression in tumour-infiltrating myeloid cells." (PMID 39325940, 2024). "This suggests that METTL3 has the potential to modulate the tumor microenvironment by regulating the translation of key tumor suppressor transcripts." (PMID 38444581, 2024).
tumor (continued). "To further elucidate the molecular mechanism of targeting METTL3 on tumour growth inhibition, we treated B16 cells with STM2457 for 5 days." (PMID 39568154, 2024). "RT-qPCR and IHC assays showed that expressions of METTL3 were elevated in GC tumor tissues compared to para-tumor tissues." (PMID 38448411, 2024). "M6A modification mediated by METTL3 is essential for the activation of tumor progression and angiogenesis mediated by TEK/VEGFA." (PMID 39295872, 2024). "METTL3 plays a significant role as a catalytic enzyme in mediating N6-methyladenosine (m6A) modification, and its importance in tumour progression has been extensively studied in recent years." (PMID 38238831, 2024). "USP13 was shown to positively promote glycolysis and tumor progression by stabilizing and deubiquitinating METTL3, which is a well-known “writer” for m6A modification, at K488 by removing K48-linked ubiquitin chains." (PMID 37151889, 2023). "METTL3 is highly expressed in distinct tumor types and boosts stemness by enhancing SOX2 mRNA stability upon m6A modification." (PMID 37149646, 2023). "We showed that anti-PD-1 treatment in METTL3 knockout NAFLD-HCC tumors provoked tumor regression by restoring IFN-γ+ and GZMB+ CD8+ T cells." (PMID 37586322, 2023). "The inhibition of METTL3 or IGF2BP3 enhanced anti-tumor immunity via PD-L1-mediated T cell activation." (PMID 36835633, 2023). "From the view of growth curve of tumor size, we apparently found that knockdown METTL3 inhibited tumor growth compared with Ctrls group (P < 0.05)." (PMID 37088992, 2023). "In macrophages, METTL3 knockout in myeloid cells facilitates tumor growth and lung metastasis, partially controlled by TAM augmentation and regulatory T cell infiltration into the tumor microenvironment." (PMID 37015927, 2023). "In bladder cancer cells, METTL3 promotes the maturation of miR-221/222 in an m6A-dependent manner, which causes PTEN reduction, leading to cell proliferation and tumor growth." (PMID 36866275, 2023). "For instance, most of the available urologic tumour studies have focused on popular methyltransferases and m6A binding proteins, such as METTL3, METTL14, YTHDFs and IGF2BPs." (PMID 37284313, 2023). "Recently, METTL3 was reported to participate in the regulation of autophagy in cardiomyocytes and tumour cells, but its role in autophagy is still controversial." (PMID 36564367, 2023). "Studies have revealed a positive correlation between the density of CD33+ MDSCs in tumor tissues and METTL3 expression." (PMID 38187373, 2023). "Nucleoside and non-nucleoside METTL3 inhibitors were designed to inhibit the function of METTL3 in different kinds of tumours and proved METTL3 was an efficient therapeutic target." (PMID 36880874, 2023). "The METTL3-mediated modification of m6A is necessary to activate TEK/VEGF-A mediated tumour development and angiogenesis in BC." (PMID 37284313, 2023). "Collectively, our findings highlight the potential clinical implications of Circ _0001187 as a key tumor suppressor in AML via the miR-499a-5p/RNF113A/METTL3 pathway." (PMID 37280654, 2023). "Previous studies have found that METTL3 regulates tumour cell proliferation and drug resistance by affecting the m6A levels of target RNAs." (PMID 37156816, 2023). "Mettl3 is involved in numerous pathophysiological functions, such as embryonic development, fat accumulation, and tumor progression." (PMID 37007040, 2023). "METTL3, known as a core subunit of the methyltransferase complex, has been reported to be involved in various biological processes including tumor progression, macrophage polarization, axonal growth, atherosclerosis, and chronic hypertrophy among others." (PMID 37151889, 2023). "Lactate accumulated in the tumor microenvironment potently promoted METTL3 upregulation in TIMs through H3K18la, and lactylation of METTL3 in TIMs promoted m6A-mediated immunosuppression." (PMID 37771377, 2023).
tumor (continued). "In DOX-resistant CML cells, LINC00470 promoted the degradation of phosphatase and tensin homolog (PTEN) mRNA via METTL3-modified methylation, which acts as a tumor suppressor by inhibiting Notch and PI3K‐AKT‐Mtor signaling." (PMID 36810281, 2023). "In tumor models, METTL3 and METTL14 were reported to redistribute and localize to the promoters or enhancers of SASP genes during the senescence process." (PMID 37015927, 2023). "The inhibition of METTL3 decreased aggressive tumor phenotypes of PDAC, potentially through the attenuation of m6A modification on the DDX23 mRNA." (PMID 37915034, 2023). "Unsurprisingly, METTL3 is a crucial hub in tumor growth and progression, regulating the splicing, stability, and expression of a wide range of genes through m6A modifications." (PMID 37996892, 2023). "Recently, an analogous result has shown that METTL3-deficiency in macrophages destroyed the translation of SPRED2 mediated by YTHDF1, which promoted tumor growth and metastasis through the activation of ERK and NF-κB/STAT3 pathways." (PMID 36960074, 2023). "Overall, high expression of Mettl3 in CC is associated with poor prognosis, but some studies have suggested that Mettl3 is beneficial in inhibiting tumor progression." (PMID 37007040, 2023). "As METTL3 can regulate the infiltration and polarization of TAMs and tumor-associated neutrophils, it is meaningful to study the therapeutic application of METTL3 in anti-tumor immune responses." (PMID 37671161, 2023). "For example, METTL3, as one of the m6A-RNA-methylation regulators, is upregulated in OSCC tissues, and high levels of METTL3 expression in tumor tissues predict poor patient survival." (PMID 36793593, 2023). "The combination of m6A-targetting drugs such as FTO- and METTL3-inhibitors alongside existing anti-cancer therapy has been shown to sensitise tumours to treatment, demonstrated in animal models of a range of cancers types." (PMID 37444417, 2023). "METTL3-mediated m6A modification has a positive regulatory effect on glycolysis in numerous tumours, although it acts on different pathways." (PMID 36859310, 2023). "Compared to patients with early-stage CC, Mettl3 expression levels were significantly higher in patients with advanced CC, suggesting a gradual increase in Mettl3 during the process of tumor malignancy." (PMID 37007040, 2023). "In contrast, the growth rate and volume of the METTL3-overexpressing H69 tumours were significantly higher than those of the control H69 tumours." (PMID 36932427, 2023). "In another study, the consumption of METTL3 or METTL14 in CT26 tumor mice with anti-PD-1 therapy significantly slowed tumor proliferation and prolonged the survival rate." (PMID 37427112, 2023). "Clinical data further showed that tumor tissues containing higher levels of METTL3, SNAI1, and YTHDF1 correlated with worse prognosis for liver cancer patients." (PMID 39872957, 2023). "And another important result of this study is to determine the causal connections among ANGPTL3 mRNA m6A levels and METTL3 expression and STAD tumor progression using bioinformatics analysis and comprehensive experiments." (PMID 37344779, 2023). "It is thus suggested that the regulatory role of METTL3 in tumor metastasis is not limited to classical metastasis-related proteins and signaling pathways." (PMID 37996892, 2023). "METTL3 is commonly aberrantly expressed in different tumors and affects the mRNA translation of many oncogenes or dysregulated tumor suppressor genes in a variety of ways." (PMID 36830614, 2023). "More researchers are needed to determine the precise mechanisms by which METTL3 promotes or suppresses tumor development." (PMID 39872957, 2023). "An m6A writer, methyltransferase-like 3 (METTL3), is modified by lactylation at its zinc-finger domain, changing its RNA capturing capacity and regulating immunosuppression of tumor-infiltrating myeloid cells." (PMID 37086786, 2023).